MIR3670-3 (microRNA 3670-3)
Synonyms: hsa-mir-3670-3
Gene: MicroRNA gene on chromosome 16 (18,405,698 to 18,405,762, reverse strand). Ensembl gene ENSG00000265776.
Homologues: Paralogues in human: MIR3670-1 (100% identical), MIR3670-2 (100% identical), MIR3670-4 (100% identical).